NEAT1 (nuclear paraspeckle assembly transcript 1)
Diseases named in the same sentence as NEAT1 in open-access papers (continued):
Sharing a sentence is not in itself a finding about the gene and the disease.
cancer (continued). "Neat1 (Nuclear Enriched Abundant Transcript), by being up regulated in various cancer tissues, was found to promote tumorigenesis and cancer progression." (PMID 29206174, 2017). "A total of 12 studies with 3,262 cancer patients were pooled in the analysis to evaluate the prognostic value of NEAT1 in multiple tumors." (PMID 29026116, 2017). "Neat1 also induces cell cycle progression in the cancer cells, along with apoptosis resistance and enhanced invasion." (PMID 29206174, 2017). "This meta-analysis is the first to explore the correlation between NEAT1 expression and prognosis of cancer patients." (PMID 28507281, 2017). "Many studies have reported that NEAT1 plays critical oncogenic roles and facilitates tumorigenesis of various human cancers." (PMID 28507281, 2017). "Normally lncRNAs exert a diverse spectrum of regulatory mechanisms, a special lncRNA NEAT1 (nuclear-enriched autosomal transcript) is mainly localized to nuclear paraspeckles, subnuclear particles that can be found in the cell nuclei of cancer cells." (PMID 29254281, 2017). "In conclusion, the meta-analysis results suggest the prognostic role NEAT1 in prognosis in the patients with different types of cancer." (PMID 27926523, 2017). "Although the results revealed the relationship between NEAT1 and OS and patients’ clinicopathological parameters, there are some limitations of this meta-analysis: the number of studies and cancer patients were limited." (PMID 28507281, 2017). "NEAT1 depleted cancer cells exhibited a much higher level of γH2A.X accumulation and this higher amount of DNA damage was exacerbated in response to replication stress." (PMID 29254281, 2017). "It is possible that NEAT1 acts to promote carcinogenesis directly by abrogating the stressors placed on the genomes of cancer cells." (PMID 29113413, 2017). "Several studies have reported that NEAT1 is aberrantly expressed in different types of cancer, including in digestive system cancers." (PMID 28118609, 2017). "A meta-analysis on the basis of published studies demonstrated that an increased expression of NEAT1 indicated a worse survival outcome in cancer patients." (PMID 28118609, 2017). "In the cancer studies, NEAT1 was found to be up-regulated in various types of cancer tissues and cancer cell lines, and NEAT1 was a key mediator in cancer progression by the regulation of cell apoptosis, cell proliferation as well as cell cycle." (PMID 27926523, 2017). "This suggested that high expression of NEAT1 was a predicator of poor prognosis among human cancers." (PMID 28507281, 2017). "Our results indicated that the expression levels of NEAT1 in cancer tissue were similar to those in adjacent non-cancer tissue." (PMID 28118609, 2017). "A recent study has illustrated that targeting NEAT1 and ‘paraspeckles’ would be a new therapeutic avenue in the fight against cancer." (PMID 29254281, 2017). "Although NEAT1-c-Met signaling is known to play a role in several cancers, our findings are the first indication that NEAT1 contributes the progression of RCC through the miR-34a/c-Met axis." (PMID 28968960, 2017). "Nuclear paraspeckle assembly transcript 1 (NEAT-1) is a lncRNA that acts as a transcriptional regulator controlling expression of many genes implicated in progression and metastasis of many cancers." (PMID 28957348, 2017).
cancer (continued). "Recently, a quantitative analysis also indicated that NEAT1 over-expression predicted worse outcome in several cancers with the pooled HR being 1.53 (95% CI: 1.36–1.71, p < 0.001) for OS33." (PMID 29026116, 2017). "In the current study, we performed the comprehensive and detailed meta-analysis to investigate the clinical prognostic role of NEAT1 with a variety of carcinomas." (PMID 29026116, 2017). "According to meta result in multivariate analysis, enforced NEAT1 expression was predictive of unfavorable OS in various carcinomas (HR = 1.79, 95% CI: 1.40–2.31, P = 0.000)." (PMID 29026116, 2017). "The authors included 11 publications, including studies on eight types of neoplasm, to evaluate the prognostic role of NEAT1 in patients with carcinoma." (PMID 28118609, 2017). "Long noncoding RNA nuclear paraspeckle assembly transcript 1 (NEAT1) plays key role in the progression of some human cancers." (PMID 26822763, 2016). "We further examined the expression of NRAS, which promotes oncogenesis in various cancers, and found that NEAT1 knockdown significantly reduced NRAS expression in GSCs." (PMID 27556696, 2016). "These were not fully in accordance with the previous findings in NSCLC or HCC, in which the proliferative, migrational, and invasive behaviors of cancer cells were all enhanced by exogenous NEAT1 expression in vitro." (PMID 26911892, 2016). "Long non-coding RNAs (lncRNAs) have also been increasingly implicated in tumor biology, yet beyond studies of previously cancer-associated transcripts such as HOTAIR, MALAT-1, and NEAT-1, their significance in HNSCC is sparsely characterized." (PMID 27323410, 2016). "NEAT1 is a novel long non-coding RNA (lncRNA) which serves as a crucial regulator in several cancers." (PMID 26911892, 2016). "NEAT1 functions as a transcriptional regulator and contributes to a cancer-favourable transcriptome, thereby promoting tumorigenesis in experimental animal models." (PMID 25415230, 2014). "It's specific overexpression within various cancers is so pronounced, NEAT1 has garnered implications that it’s expression may be used as a form of biomarker for identifying malignant tissues, as was outlined in a recent study in prostate cancer." (PMID 40521240, 2025). "Adeno-associated virus (AAV)-mediated delivery holds promise for DMD therapy, supported by precedents in other diseases where AAV vectors delivered lncRNAs like H19 (cancer), Malat1 (vascular disease), and Neat1 (neurological disorders) to achieve therapeutic effects." (PMID 40649811, 2025). "NEAT1’s functional mechanism involves multiple facets related to gene activity control, cellular structure and function modifications, and interactions with other elements that facilitate cancer growth." (PMID 41013839, 2025). "MALAT1 and NEAT1 regulate various cellular processes, the inflammatory response, and resistance to anti-cancer treatments; however, their impact on the portability of post-RT adverse effects remains unknown." (PMID 40150019, 2025). "MALAT1, NEAT1, and HOTAIR integrate stress signals with chromatin, transcriptional, and post-transcriptional control, and have been separately linked to apoptosis and autophagy in several cancers." (PMID 41373437, 2025). "NEAT1 can also be transcriptionally upregulated by hypoxia in non-cancer cells." (PMID 40362651, 2025). "The authors also showed that NEAT1 stimulated cancer cell proliferation and invasion in vitro." (PMID 41373437, 2025). "Recent research has shown the role of NEAT1 in the development of a variety of types of cancer." (PMID 41244835, 2025). "In several cancer types, altered expression patterns of NEAT1 and miR-129-5p have been documented." (PMID 40730640, 2025). "Moreover, there are evidences indicating the relationship between NEAT1, the skeletal lncRNA of paraspeckle, and microtubule stabilization or cancer proliferation." (PMID 40360465, 2025).
cancer (continued). "Recent studies have observed two isoforms of NEAT1, the shorter isoform NEAT1_1 (3.7 kb in human) and the longer isoform NEAT1_2 (22.7 kb in human), which each display different roles in regulating the different phenotypes in cancer cells." (PMID 40231344, 2025). "Thus, collectively, these findings revealed that lincNEAT1 encodes NEAT1‐31, which is particularly enriched within antitumor macrophages and predicts a good ICB response across multiple cancers." (PMID 40344649, 2025). "Notably, the Neat1 isoform switching has been demonstrated to play a role in some cancers, although the oncogenic relevance of the two isoforms needs to be further clarified." (PMID 40352720, 2025). "NEAT1 also regulates ferroptosis in cancer and neurological disorders." (PMID 41268533, 2025). "In a xenograft model, knockdown of NEAT1 reduces tumor growth and induces cancer cell apoptosis." (PMID 40231344, 2025). "Although isoform‐specific contributions are still unknown, studying both could be effective in determining the role of NEAT1 as a tumor promoter or tumor suppressor in cancer." (PMID 40231344, 2025). "Furthermore, NEAT1 is essential for the stability of the MUC1-CT protein, suggesting that NEAT1 probably helps to maintain the oncogenic activity of MUC1-CT in cancer cells." (PMID 40001578, 2025). "NEAT1, or nuclear-enriched autosomal transcript 1, is involved in the carcinogenesis of cancer." (PMID 39337410, 2024). "NEAT1 derived from BC paclitaxel-resistant SKBR-3/PR cell exosomes can induce paclitaxel resistance by regulating the GO/G1 phase of the cell cycle.CXCL12 plays an important regulatory role in promoting cancer chemotherapy resistance." (PMID 38970092, 2024). "NEAT1 can affect the chemotherapy resistance of cancer by promoting aerobic glycolysis." (PMID 38970092, 2024). "NEAT1 can induce chemotherapy resistance by promoting the cell cycle progression of cancer cells." (PMID 38970092, 2024). "Histogram of GO and KEGG analysis showed that independent DEGs of silenced NEAT1 were more significantly enriched in organelle, catalytic activity, cancer, cell growth and death, signal transduction, and amino acid metabolism compared to the independent DEGs of silenced NEAT1_2." (PMID 38898019, 2024). "The lncRNA NEAT1 is a well-documented lncRNA in different types of cancer." (PMID 39246994, 2024). "A dysregulation of NEAT1 has been revealed in various human cancer specimens, which may serve as a potential biological factor for tumor diagnosis and prognosis." (PMID 39061140, 2024). "These and numerous other studies have revealed the complex roles of NEAT1 in cancers." (PMID 39032650, 2024). "NEAT1 functions as an oncogene in many cancers, including HCC, in which it is overexpressed." (PMID 38203767, 2024). "Moreover, multiple studies have suggested key roles for lncRNAs MALAT1, LINC-PINT and NEAT1 in cancer, and in therapeutic resistance in breast cancer." (PMID 39199690, 2024). "Previous studies have examined the abundance and function of NEAT1 in an array of cancers." (PMID 39032650, 2024). "Paraspeckles, and hence NEAT1, play a role in the nuclear retention of mRNAs, function as molecular sponges for RBPs, and regulate key physiological and pathological processes, such as corpus luteum formation, and cancer." (PMID 38203767, 2024). "In previous studies, the PI3K/AKT pathway was shown to be a classical oncogenic signaling pathway that is involved in the occurrence, development and chemotherapy resistance of various tumors, and downregulated expression of NEAT1 inhibited the PI3K/AKT/mTOR signaling pathway in many cancer cells." (PMID 38898019, 2024). "Sixteen lncRNAs were of unknown function, six were described in cancer, one connected with macrophages polarisation, and four were associated with CVDs, mainly with SMC function and phenotypic switch (NEAT1, MIR100HG, HIF1A-AS3, and MRI29B2CHG)." (PMID 38616192, 2024). "NEAT1 can enhance chemotherapy resistance of cancer cells by inducing autophagy." (PMID 38970092, 2024).
cancer (continued). "Therefore, the dysregulation of NEAT1 can be regarded as a robust and credible adverse prognostic factor in human cancer, which will help to develop effective strategies for the diagnosis, treatment and prognosis of cancer in the future." (PMID 38970092, 2024). "We found that MUC1-C and NEAT1 contribute to cytotoxic drug resistance in different cancer models." (PMID 38802648, 2024). "NEAT1 promotes the process of EMT, which is linked to metastasis and cancer cell invasiveness." (PMID 39578854, 2024). "Most cancer patients with high NEAT1 expression often indicate poor prognosis and shorter survival." (PMID 38970092, 2024). "Therefore, a detailed elucidation of NEAT1‐miRNA regulatory pathways and the impact of their interactions on cancer progression will shed light on the development of novel therapeutic approaches via targeting these potential biomarkers." (PMID 38577722, 2024). "The subnetwork analyses showed that NEAT1, MALAT1, and OIP5-AS1 are associated with genes involved in cancer-related pathways, including the "mTOR signaling pathway," "AMPK signaling pathway", and "PI3K-Akt signaling pathway", as identified in KEGG pathway analysis." (PMID 39246994, 2024). "Comprehensive studies in larger patient cohorts with detailed genomic analysis are essential to confirm the regulatory roles of NEAT1 and MALAT1, contributing to a comprehensive understanding of how APOBEC3 enzymes promote cancer evolution by causing genome and transcriptome heterogeneity." (PMID 39322638, 2024). "In addition, some non-coding RNAs, such as LINC01087 56, TUG1 27, NEAT1 57 and circ_0020123 58, were verified to target miR-384 in cancer progression." (PMID 39132166, 2024). "NEAT1 is a nuclear paraspeckle-localized lncRNA found in a variety of cancers." (PMID 39257589, 2024). "Interactions between NEAT1 and shelterin may impact this balance, resulting in telomere extension and the avoidance of cellular senescence, which is a crucial aspect of cancer cell longevity." (PMID 39578854, 2024). "NEAT1 exhibits significant involvement in cellular proliferation across diverse cancer types." (PMID 38343745, 2024). "In further support of the MUC1-C/XIST pathway, we found that MUC1-C and XIST regulate common genesets associated with activation of (i) miRNAs, such as miR-21, (ii) lncRNAs NEAT1 and MALAT1, and protein encoding genes that are linked to inflammation and dysregulated in cancer." (PMID 38740827, 2024). "Consequently, disrupting the feedback loop within the NEAT1/miRNA/target axis offers a promising avenue to surmount therapeutic resistance challenges in cancer treatment." (PMID 38343745, 2024). "NEAT1 can promote chemotherapy resistance of cancer cells by regulating the EMT process." (PMID 38970092, 2024). "Besides, suppression of NEAT1 resulted in decreased CD44high, CD24low, ALDHhigh, and SOX2high cancer stem cells populations, a population with self‐renewal and multilineage differentiation properties." (PMID 37795578, 2023). "Over the years, research has shown that NEAT1 is aberrantly upregulated in a variety of cancers." (PMID 37759495, 2023). "The lncRNA NEAT1 reduces the expression of CTR1 to regulate the function of cancer stem cells." (PMID 36755568, 2023). "NEAT1 knockdown reduced the proliferation of MCF-7 or SK-BR-3 cells in colony formation assay, while simultaneous transfection of cancer cells with small interfering RNA against NEAT1 (si-NEAT1) and miR-218 inhibitor showed an opposite effect on cell proliferation." (PMID 37310654, 2023).
cancer (continued). "Expression of the long noncoding RNA (lncRNA) nuclear paraspeckle assembly transcript 1 (NEAT1) is regulated with functional ERα signaling, and cancers of the prostate that originate in NEAT1-positive epithelial cells are resistant to androgen inhibitors and androgen deprivation." (PMID 37760622, 2023). "Furthermore, several genes whose expression predicts the poor prognosis of many cancer types and represents potential anticancer targets, i.e., Lgals3, Smox, Ndrg1, Neat1, and Rbm39, were significantly upregulated in most of the KO cell types." (PMID 37809094, 2023). "Thus, the mechanisms by which NEAT1 plays a critical role in cancers is through the NEAT1/miRNA/mRNA axes." (PMID 37175800, 2023). "Several lncRNAs, such as MALAT1, HOTAIR, PVT1, NEAT1, ANRIL, and SPRY4-IT1, have recently been identified, particularly in cell lines, liquid biopsy, and tissue biopsy samples and have been associated with cancer pathogenesis." (PMID 37424727, 2023). "Thereby, the role of NEAT1 in chemoresistance and cancer stemness proposed that NEAT1 could be applied as a promising clinical curative target for patients with drug resistance." (PMID 37310654, 2023). "Since NEAT1′s oncogenic role in other tumor types goes beyond miRNA sponging, also involving interactions with RBPs to form paraspeckles and to impact gene regulation and cancer progression, these interactions need to be investigated in the context of MB." (PMID 37835380, 2023). "Furthermore, several cancer-promoting or tumor-suppressing lncRNAs, such as NEAT1, H19, NRON, LUCAT1, and HOTAIR, can be found not only in malignant cells but also in tumor-specific immune cells." (PMID 36911393, 2023). "NEAT1 is a pan‐cancer LncRNA18 and contributes to the development of HCC." (PMID 37752791, 2023). "Although the expression of NEAT1 was found to be increased in cancer cells, the exact roles of NEAT1 remain largely unknown and further studies are required to confirm this hypothesis." (PMID 37310654, 2023). "NEAT1 has been shown to play an oncogenic role in many kinds of cancers." (PMID 36434587, 2022). "NEAT1, a long non-coding RNA, functions as an oncogene in diverse cancers." (PMID 36050752, 2022). "Subsequently, the elevation of NEAT1 contributes to cancer progression." (PMID 36011001, 2022). "miR-3158-5p was negatively associated and RAB3B was positively associated with cancer stage, while NEAT1 was positively associated with cancer stage, but without statistical significance." (PMID 35664777, 2022). "NEAT1 has been previously found perturbed (up or downregulated) at the gene-level in metformin-treated cells, and the predicted function of this gene in response to treatment can differ depending on the cancer cell line." (PMID 36287120, 2022). "NEAT1 can also reduce cancers’ sensitivity to chemotherapy or radiotherapy." (PMID 36011001, 2022). "In many cases, NEAT1, as a ceRNA, inhibited miR-27b-3p, miR-101-3p, miR-193-3p, and miR-204 to augment or attenuate the radioresistance of cancer cells." (PMID 35054896, 2022). "Furthermore, plant miRNAs have also been reported to reduce cancer-cell proliferation by targeting MALAT1 (Metastasis-associated lung adenocarcinoma transcript 1) and NEAT1 (Nuclear-enriched abundant transcript 1)." (PMID 35456943, 2022). "In the context of cancer, NEAT1 may have either a protective, tumour-suppressive role, or a tumour-promoting oncogenic role, depending upon the type of cancer and, most likely, also upon the specific NEAT1 isoform expressed." (PMID 36139550, 2022). "Accumulating studies revealed that NEAT1 functions as an oncogenic molecule in various cancers." (PMID 35313796, 2022). "A higher level of NEAT1 almost always indicates a poorer survival rate in cancer patients." (PMID 36011001, 2022). "In this research, we hypothesized that NEAT1 exerted cancer-promoting effects on PTC and NEAT1 controlled the new miRNA/mRNA networks to mediate PTC development." (PMID 35635748, 2022).